TPO (thyroid peroxidase)
Diseases named in the same sentence as TPO in open-access papers (continued):
Sharing a sentence is not in itself a finding about the gene and the disease.
autoimmune thyroid disease (continued). "Already in 1990 it was proven that using Tg or TPO as antigens induced experimental autoimmune thyroiditis in mice, which suggested that these antigens might play a role in the pathogenesis of HT in humans." (PMID 26000316, 2015). "Numerous authors are inclined to believe that coexistence of lymphocytic infiltrations, positive history of thyroid autoimmune diseases, or significantly high antibody levels (anti-TPO, anti-TG) prior to surgery had a significant impact on prognosis improvement." (PMID 23099542, 2013). "Anti-TPO and, to a lesser extent, anti-TG are sensitive tests for assessing thyroidal autoimmunity." (PMID 23476155, 2013). "Evidence of thyroid autoimmunity is common in individuals with type 1 diabetes mellitus, with up to 27% of young adults with type 1 diabetes mellitus having detectable titers of anti-thyroid peroxidase antibodies." (PMID 21722403, 2011). "Various thyroid autoantibodies including thyroid stimulating antibody, anti- thyroglobulin antibody and anti-thyroid peroxidase antibody, are detectable in autoimmune thyroid diseases the latter being the most sensitive test for the diagnosis and follow-up of this group of diseases." (PMID 16526964, 2006). "In this study, we assessed the frequency of anti-TPO as a sensitive marker of autoimmune diseases of the thyroid in vitiligo patients and compared it with healthy subjects in order to find data further supporting the autoimmune theory in the pathogenesis of vitiligo." (PMID 16526964, 2006). "This is probably due to anti-TPO and anti-TG class IgG antibodies freely crossing the placental barrier from mid gestation, although this passage decreases as pregnancy progresses because of the lowering of maternal-foetal transfer owe to suppression of thyroid autoimmunity over time." (PMID 40128881, 2025). "In addition, a positive correlation was found between Anti-TPO and T3 (r = 0.311, p = 0.040), indicating that T3 levels increase with increasing Anti-TPO levels, and thyroid autoimmunity may affect thyroid hormone levels." (PMID 38892793, 2024). "In the present study, we investigated whether the presence of thyroid autoimmunity alone and the level of thyroid peroxidase IgG autoantibodies may be helpful to predict the response to omalizumab in clinical practice, thus discriminating patients with probable severe type I or type IIb CSU." (PMID 37108654, 2023). "Chronic lymphocytic thyroiditis, also known as Hashimoto’s thyroiditis, is an autoimmune thyroid disease which presents with inflammatory cell infiltration of the thyroid gland and is characterised by the production of autoantibodies to thyroglobulin (anti-TG) and thyroperoxidase (anti-TPO)." (PMID 34573074, 2021). "Finally, because autoantibody (and possibly T cell) responses to TPO are similar to those to TSH receptor and thyroglobulin, manipulating T and B cell responses to TPO could pave the way for immunospecific treatment of autoimmune thyroid disease in general." (PMID 34667679, 2021). "Consequently, patients present with a constellation of physical and neuropsychiatric findings (i.e. musculoskeletal complaints, depression, free-floating anxiety, memory deficits), and in cases of thyroid autoimmunity, formation of anti-bodies to thyroglobulin (Tg) and thyroid peroxidase (TPO)." (PMID 26301086, 2015). "In conclusion, these data show that thyroid autoimmunity and dysfunction are present in this group of diabetic children and strengthen the argument for routine screening of all diabetic children and adolescents for thyroid autoimmunity (particularly anti-TPO) as recommended by consensus guidelines." (PMID 25767657, 2014). "In addition to T1D, 15 patients developed autoimmune thyroid disease, i.e., Hashimoto’s thyroiditis (APS3v), confirmed by the presence of circulating Tg and TPO Abs and by an echographic pattern of diffuse hypoechogenicity, and 1 of these patients also presented vitiligo." (PMID 25333705, 2014).
autoimmune thyroid disease (continued). "The term autoimmune thyroid disease encompasses a number of different entities characterized by varying degrees of thyroid dysfunction and the presence of serum autoantibodies against thyroid tissue-specific components, such as thyroglobulin (Tg) and thyroid peroxidase (TPO)." (PMID 22545223, 2012). "If the findings are confirmed, they may prove to be of interest for future projects of case finding: a systematic screening for mood disorders in anti-TPO+ subjects and a systematic evaluation for thyroid diseases and thyroid autoimmunity in subjects with mood disorders may be advisable." (PMID 15317653, 2004). "Autoantibodies against glutamic acid decarboxylases (GAD1 and GAD2), characteristic of T1D, and against thyroid peroxidase (TPO) and thyroglobulin, which are frequently present in APECED patients with autoimmune thyroid disease, are also prominent." (PMID 41461613, 2026). "Prior studies have reported elevated rates of thyroid autoantibody abnormalities such as TPO-Ab and TG-Ab in patients with SSNHL, and some data suggest a link between thyroid autoimmunity and more severe high frequency HL." (PMID 40826678, 2025). "Thyroid peroxidase (TPO) antibodies, organ-specific autoantibodies and serological indicators for autoimmune thyroiditis (Hashimoto’s thyroiditis), are frequently elevated in patients with SREAT." (PMID 40149702, 2025). "The absence of this association in anti-TPO-positive subjects suggests that thyroid autoimmunity may disrupt the metabolic effect of reduced thyroid hormone sensitivity, possibly through mechanisms involving low-grade inflammation or subtle thyroid dysfunction." (PMID 40600010, 2025). "Hashimoto’s thyroiditis (HT), characterized by the production of anti-thyroglobulin (TG) and anti-thyroid peroxidase (TPO) antibodies, is the most common autoimmune thyroid disease in children." (PMID 39968296, 2025). "In our study, elevated anti-TPO antibody levels were observed in 51.2% of CSU patients, compared to only 6% in the control group, highlighting the increased prevalence of thyroid autoimmunity in this population." (PMID 40075855, 2025). "Anti-TPO is the most sensitive parameter in detecting autoimmune thyroid diseases, as TPO (thyroid peroxidase) is the primary antigen of thyroid cell microsomes." (PMID 39519244, 2024). "Thyroid peroxidase (TPO) antibodies, a key marker for autoimmune thyroid disease, are highly prevalent in 40–45% of women with TS." (PMID 39198906, 2024). "Cross-reactivity between thyroid peroxidase (TPO) and lactoperoxidase (LPO) due to their structural similarities can also contribute to thyroid autoimmunity." (PMID 38952602, 2024). "Psoriasis has known multi-organ involvement, and an association between thyroid dysfunction and thyroid autoimmunity in psoriatic arthropathy subjects has been suggested, though no clear-cut association between TPO Ab positivity and psoriatic disease could be established in the study." (PMID 38192953, 2023). "The autoimmune thyroid disease was screened by monitoring T3, T4, TSH, and anti-TPO antibody levels." (PMID 37378208, 2023). "Thyroid autoimmunity (TAI), defined by the presence of circulating antithyroid antibodies targeting thyroid peroxidase (TPOAb) and thyroglobulin (TgAb), is prevalent among women of reproductive age and is the most frequent cause of thyroid dysfunction." (PMID 35721757, 2022). "Background and Aims: Thyroid peroxidase (TPO) is a key enzyme in the synthesis of thyroid hormones and a major autoantigen in autoimmune thyroid disease." (PMID 35869534, 2022). "Anti-thyroid peroxidase antibodies (anti-TPO) and anti thyroglobulin antibodies (anti-TG) are basic markers of thyroid autoimmunity as Hashimoto’s thyroiditis (HT)." (PMID 33750377, 2021). "A majority of patients also have measurable autoantibodies against thyroid peroxidase (TPO ab), a vital enzyme in thyroid-hormone synthesis, as a marker for autoimmune thyroid disease." (PMID 31963883, 2020).
autoimmune thyroid disease (continued). "However, a recent study finds the prevalence of Tg-abs (but not TPO-abs) is related to a lower risk of readmission in BD, suggesting Tg-abs might play a part in the association between autoimmune thyroiditis and BD." (PMID 31791284, 2019). "Thyroid autoimmunity (TAI), which is defined as the presence of autoantibodies against thyroid peroxidase (TPO) and/or thyroglobulin (TG), is related to repeated implantation failure (RIF)." (PMID 26308040, 2015). "With reference to thyroid autoimmunity, 30/44 participants in the NET group demonstrated higher than the normal concentrations of TPO-Ab and 12/44 demonstrated higher than normal concentrations of Tg-Ab." (PMID 26301086, 2015). "Thyroid autoimmunity (TAI), which is defined as the presence of anti-thyroid peroxidase (anti-TPO) and/or anti-thyroglobulin (anti-TG) antibodies, is one of common autoimmunity disorders affecting 5%–20% of normal pregnant women." (PMID 26308040, 2015). "Organ-specific antibodies, such as anti-thyroglobulin (anti-TG) and anti-thyroid peroxidase antibodies (anti-TPO), most characteristic for autoimmune thyroiditis, were also found." (PMID 24985362, 2015). "In the present study, thyroid autoimmunity was significantly higher in patients with T1DM than in healthy controls; the prevalence rates of anti-TPO and anti-Tg antibodies in T1DM patients of our study were 25.3% and 47.5% respectively." (PMID 22029731, 2011). "Third, our dataset did not include information on thyroid antibody levels (e.g., TPO and thyroglobulin antibodies) or autoimmune thyroid disease diagnoses." (PMID 39941590, 2025). "In both patients, the laboratory workup revealed negative autoantibodies for thyroglobulin (TGAb), anti-thyroid peroxidase (TPOAb) and thyroid-stimulating hormone receptor (TSHRAb), excluding Graves’ disease or thyrotoxicosis by autoimmune thyroiditis." (PMID 39565383, 2025). "Thyroid function tests revealed elevated thyroid-stimulating hormone (TSH) with low T3 and low-normal free T4, serology was positive for anti-TPO and anti-TSHR antibodies, and ultrasound revealed features suggestive of thyroiditis, confirming autoimmune thyroid disease." (PMID 40861566, 2025). "Autoimmune thyroiditis was unlikely, as thyroid peroxidase and thyroglobulin antibodies were negative." (PMID 41446490, 2025). "For instance, the SARS-CoV-2 spike protein, nucleocapsid protein, and membrane protein have all been found to cross-react with thyroid peroxidase (TPO), which may contribute to the development of autoimmune thyroid diseases." (PMID 40575205, 2025). "Imaging is not routinely done; however, antithyroid antibodies such as thyroid peroxidase antibodies should also be assessed to evaluate for autoimmune thyroid diseases, especially if this is the first presentation without a diagnosis." (PMID 41523526, 2025). "The pathophysiology of Hashimoto’s thyroiditis involves the destruction of thyroid follicular cells through the action of autoantibodies, such as anti-thyroid peroxidase (anti-TPO) and anti-thyroglobulin antibodies (anti-TG), which play a key role in confirming the diagnosis of thyroid autoimmunity." (PMID 40332182, 2025). "Thyroid autoimmunity (TAI) is defined as the presence of thyroid peroxidase antibodies (TPO-Ab) or thyroglobulin antibodies (TG-Ab), regardless of thyroid function." (PMID 41377941, 2025). "For thyroid autoimmunity, we assessed anti-thyroid peroxidase (anti-TPO) antibodies in 87 individuals, where 61 tested negative and 33 were positive." (PMID 40650029, 2025). "Additionally, the co-occurrence of autoimmune thyroid disease, particularly HT (characterized by elevated TSH, low free T4, and positive TPO antibodies), is frequently reported in patients with LADA due to shared autoimmune etiology." (PMID 41024896, 2025). "Thyroid peroxidase (TPO) antibody levels were subsequently tested and found to be negative, reducing the likelihood of autoimmune thyroiditis." (PMID 40718313, 2025).
autoimmune thyroid disease (continued). "However, in patients with autoimmune thyroiditis, percentages of anti-NIS antibodies are lower than those of anti-TPO and Tg antibodies." (PMID 41516079, 2025). "It further explores the correlation of eGFR between Anti TPO positive and negative elderly hypothyroid patients to provide new insights into the interplay between thyroid autoimmunity and renal function in this population." (PMID 40937419, 2025). "Additionally, it was observed that individuals with positive TPO-Abs (Antibodies to Thyroid Peroxidase) coexists with low TSH levels were particularly vulnerable to developing dementia, which reminds us of the importance of autoimmune thyroid disease in AD." (PMID 38419953, 2024). "First, we did not measure autoimmune thyroid factors such as anti-TPO antibodies, and a thyroid ultrasound was not performed on the study participants to compare the prevalence of autoimmune thyroiditis in the two groups." (PMID 36673125, 2023). "Third, TPO Ab, the most sensitive marker for evaluating autoimmune thyroid disease, was not measured in this study." (PMID 38011178, 2023). "IL‐31 levels were higher in CSU patients with thyroid autoimmunity (assessed by anti‐TPO and/or anti‐TG) than in patients without thyroid autoimmunity, but the difference was not statistically significant." (PMID 37632245, 2023). "A previous study on subjects without thyroid autoimmunity at baseline found that the abdominal obesity phenotype had no significant impact on the development of TPO-Ab positivity over time." (PMID 36967773, 2023). "Thyroid autoimmunity has been considered indicative of a type IIb autoimmune CSU phenotype, and the recent PURIST study found that type IIb CSU patients tend to have high levels of TPO autoantibodies." (PMID 37108654, 2023). "Unfortunately, we did not measure autoimmune thyroid parameters such as anti-TPO antibodies, and a thyroid ultrasound was not performed on the study participants to compare the prevalence of autoimmune thyroiditis in the two groups." (PMID 36673125, 2023). "We studied the prevalence of overt hypo- and hyperthyroidism and thyroid autoimmunity using medical histories, and measurements of TSH, FT4, anti-TPO and anti-TG, comparing participants exposed to famine at different pregnancy trimesters or born before or conceived after the famine." (PMID 35846325, 2022). "In our study, Tg levels were not measured but thyroid autoimmunity did not develop during 12-month follow-up in anti-Tg and anti-TPO negative patients." (PMID 35651913, 2022). "Another limitation is that thyroid peroxidase (TPO) antibodies were not measured; therefore, we were not able to distinguish autoimmune thyroid diseases." (PMID 34501256, 2021). "In the population-based studies, most participants with and without markers of thyroid autoimmunity - mostly TPO-abs - had a normal thyroid function." (PMID 34027377, 2021). "Anti-thyroid peroxidase (TPO)antibodies have been reported to be elevated in T1D and could indicate or prognose thyroid autoimmunity." (PMID 33042112, 2020). "Hashimoto’s thyroiditis (HT), an autoimmune thyroid disease (AITD), is characterized by infiltration of thyroid antigen-reactive T cells and by the presence of autoantibodies against thyroid antigens (thyroid peroxidase, TPO; thyroglobulin, Tg)." (PMID 31979029, 2020). "In addition it has been shown that thyroid autoimmune disease may be associated with a general autoimmunity, leading to premature ovarian failure; however the main pathophysiology linking ovarian reserves with TPO antibody and thyroid hormones has not been elucidated." (PMID 31064360, 2019). "Our current study proposed that a subtype of anti-TPO and anti-Tg Ab double-negative autoimmune thyroiditis was induced by nivolumab more frequently in Japan than in Western countries." (PMID 29884162, 2018).
autoimmune thyroid disease (continued). "Nevertheless, TPO-Abs are considered clinically useful serum markers of a developing or ongoing autoimmune thyroiditis (AITD) and they often precede the clinical thyroid failure phase (i.e., raised TSH, reduced fT4) of autoimmune thyroiditis for many years." (PMID 28108944, 2017). "Three female participants (ages 37, 54, and 57 years old) had elevated TPO antibodies, which are markers for thyroid autoimmunity, but their TFT values were within normal ranges (data not shown)." (PMID 26372669, 2016). "Studies on the prevalence of anti-thyroid peroxidase (anti-TPO) and anti-thyroglobulin (anti-TG) antibodies indicate that thyroid autoimmunity significantly affects the well-being of the pregnant mother as well as the fetus independently of the thyroid dysfunction." (PMID 26124747, 2015). "We found that 26.6% of MS patients treated with IFN-β1a without preexisting autoimmunity had anti-TPO, indicating that thyroid autoimmunity occurs more frequently in MS patients treated with IFN-β1a than untreated MS patients and healthy controls." (PMID 24963444, 2014). "Considering the significant association between HCV infection and autoimmune thyroid diseases (AITD), the detection of TPO-Ab and TG-Ab in all HCV patients, independent of IFN therapy, is suggested." (PMID 23383326, 2013). "Although we did not measure thyroid peroxidase antibodies, we presume this patient had long-standing autoimmune thyroiditis." (PMID 23725039, 2013). "A link between enhanced anti-thyroid autoimmunity and the occurrence of EAATD seems to be a realistic hypothesis as suggested by the positive anti-TPO Abs." (PMID 20426819, 2010). "However, with normal TSH levels and negative Anti-Thyroid Peroxidase (TPO) antibodies, this was interpreted as evidence of subclinical thyroid autoimmunity without active Graves’ disease." (PMID 41589093, 2026). "Clinically, this endotype may justify targeted screening for thyroid autoimmunity (anti-TPO, anti-TG), while non-thyroid autoantibodies are insufficiently studied and require prospective validation." (PMID 40943118, 2025). "Also, not all patients did Anti-TPO and anti-TG antibodies; we were only able to diagnose autoimmune thyroiditis but not classify them to Hashimoto thyroiditis or Graves’ disease." (PMID 41044753, 2025). "This study did not evaluate autoimmune thyroid markers such as anti-TPO antibodies." (PMID 40468332, 2025). "In addition, the common autoimmune thyroiditis auto-antibodies, including anti-thyroglobulin (TG) and anti-thyroid peroxidase (TPO) antibodies, were not involved in the subsequent analysis due to their inaccessibility." (PMID 38708097, 2024). "This study aimed to examine whether the autoimmune thyroid disease (AITD) autoantibodies, anti-thyroid peroxidase antibody (TPOAb), and anti-thyroglobulin antibody (TgAb), associate with hand OA and symptomatic hand OA in the Third National Health and Nutrition Examination Survey (NHANES III)." (PMID 39228802, 2024). "However, our results do not exclude the possibility of new-onset thyroid autoimmunity after COVID-19, and further investigations are required to clarify the etiological link between highly elevated anti-TPO titers and long COVID." (PMID 39450181, 2024). "Additionally, the evaluation for autoimmune thyroid diseases with the levels of antithyroid antibodies such as thyroid peroxidase antibodies was not performed." (PMID 36204014, 2022). "This could have resulted in some women without thyroid autoimmunity being misclassified in the TPO Ab-positive category." (PMID 31288798, 2019). "In addition, a recent study revealed that smokers had lower levels of thyroid peroxidase antibodies (TPO Ab) than non-smokers, suggesting a lower prevalence of autoimmune thyroid disease in smokers than non-smokers." (PMID 30862792, 2019).